RN7SL702P (RNA, 7SL, cytoplasmic 702, pseudogene)
Gene: Miscellaneous RNA gene on chromosome Y (12,273,473 to 12,273,764, forward strand). Ensembl gene ENSG00000243980.
Homologues: Orthologues: chimpanzee Metazoa_SRP (97% identical), macaque Metazoa_SRP (82% identical). Paralogues in human: RN7SL578P (82% identical), RN7SL1 (75% identical), RN7SL2 (74% identical), RN7SL45P (74% identical), RN7SL597P (74% identical), RN7SL709P (74% identical), RN7SL664P (73% identical), RN7SL3 (73% identical), RN7SL47P (72% identical), RN7SL126P (72% identical), RN7SL383P (72% identical), RN7SL732P (72% identical), and 699 more.